CCR2 (C-C motif chemokine receptor 2)
Diseases named in the same sentence as CCR2 in open-access papers (continued):
Sharing a sentence is not in itself a finding about the gene and the disease.
infection (continued). "We hypothesize that CCR2+ monocytes not only serve as a critical cytokine-producer cell, but that their derivative cells, Mo-Mac and Mo-DC (both CD11c+ cells) could also be important for T cell re-expansion in vaccinated mice after H99 infection." (PMID 39324785, 2024). "In the current study, we use genetically modified mice to target CCR2 and Stat1 pathways, with the aim of investigating the role of both innate and adaptive immune responses in clearing oral papillomavirus, using our established papillomavirus (MmuPV1) infection model." (PMID 38133335, 2023). "However, CCR2 knockout mice are not more susceptible to infection by a lineage 4 Mtb strain, which genetically lacks PGL, and while CCR2 knockout mice do display enhanced susceptibility to a lineage 2 strain (HN878), this outcome is PGL independent." (PMID 36419223, 2023). "No sex difference was found in NK cells among B6, Stat1ko, and CCR2ko mice (p > 0.05, Mann–Whitney rank sum test), suggesting that accumulation of NK cells in the tongue is not differentially regulated in normal and CCR2- or Stat1-deficient mice during viral control of MmuPV1 infection." (PMID 38133335, 2023). "In addition to chemotaxis, adhesion molecules such as ICAM-1, CD11b, and CD44 could be mediating CCR2+Ly6C+ monocyte trafficking to sites of infection as it was shown in the liver of primary Lm-infected mice." (PMID 34516896, 2021). "Moreover, MCK-2 mutant viruses were more efficiently controlled in the spleen and liver in a NK cell and T cell dependent manner and they provoked stronger T cell responses, in part because fewer CCR2+ inflammatory monocytes were recruited to the site of infection." (PMID 33508041, 2021). "The fact that both IFNγ and chemokines need to be spatially and temporally targeted on CCR2+Ly6C+ monocytes at sites of infection to promote their effector responses may represent an evolutionarily conserved mechanism to prevent systemic tissue damages to the host." (PMID 34516896, 2021). "Consistent with the role of CCR2 found in host responses to other pathogens, CCR2 was important in permitting differentiation of inflammatory monocytes into monocyte-derived DCs that in turn recruited activated CD4+ T cells to the lungs during IN LVS infection of mice." (PMID 33760886, 2021). "Thus, the aim of this study was to analyse SNPs in CCR2 and CCR5 and their association with CCC in patients who attend to health centers of Buenos Aires and populations from endemic area as the Gran Chaco ecoregion, with a high prevalence of infection." (PMID 30650073, 2019). "The severe down-regulation of CCR2 after direct exposure of monocytes from both seropositive and seronegative humans to the parasite might further contribute to a reduced recruitment of human monocytes to sites of infection or injury." (PMID 31316920, 2019). "As CCR2 deficiency did not interfere with macrophage accumulation in this model, we next asked if tissue-resident macrophage proliferation was occurring in response to infection." (PMID 31455692, 2019). "Therefore, pre-existing immunity and infection status alter the phenotype of the inflammatory CD64low-highCX3CR1+ monocyte population in the skin, with secondary sites of infection containing monocytes with higher Ly6C expression and lower CCR2 expression." (PMID 28666021, 2017). "We found that Ccr2-/- mice were not only deficient in Ly6Chi monocytes but also lacked CD11c+MHCII+ DCs by 48 hours post-infection with L. pneumophila, consistent with previous findings demonstrating that Ly6Chi monocytes differentiate into DCs in inflamed tissues." (PMID 28384349, 2017). "The absence of CCR2 leads to deficiencies in monocyte recruitment to the site of infection." (PMID 26973640, 2016). "Thus, CCR2+ monocytes could limit virus spread by “sopping up” infectious virus and preventing infection of cell types capable of propagating new virions." (PMID 26991092, 2016).
infection (continued). "The maintenance of a minimal level of CCL2 following AFSC treatment, may be critical for the protection of the homeostatic arm of the CCL2/CCR2 signaling pathway which not only participates in immune cell recruitment to areas of infection but also osteoclast differentiation and metabolic regulation." (PMID 23967234, 2013). "Infection disrupted the balance between macrophagesubsets in bothWT and ST2–/– mice, with an expansion ofMHC-II+CCR2+ macrophages." (PMID 41365681, 2026). "The most notable change was observedin the MHC-II+CCR2+ subset,which expanded significantly only in ST2–/– mice during infection." (PMID 41365681, 2026). "Previous studies have shown that BPD-induced damage enhances the function of chemokines and their receptors (e.g., CXCL3, CCR1, CCR2, CCR5), which direct immune cells to sites of infection or injury." (PMID 41345109, 2025). "We next quantified viable Mtb bacilli in the lungs of Het, Ccr2 and Cx3cr1 single knockouts, and DKO mice at 4 weeks post-infection." (PMID 40497732, 2025). "The infection-induced activation of cell motility was dependent on both CXCR2 and CCR2, and IL-8 stimulated filopodia-mediated cell motility." (PMID 40353220, 2025). "CCR2 inhibition reduced ESAT-6 expression and restored Beclin-1 levels in lung tissue, alleviating inflammation and injury during late-stage infection." (PMID 41562082, 2025). "Classical monocytes are recruited to infection and inflammation sites via the CCL2/CCR2 pathway, releasing cytokines like TNF-α and iNOS to kill pathogens and enhance adaptive immunity." (PMID 40370772, 2025). "In murine infection models with Japanese encephalitis virus, recruitment of T-cells is mediated via CCR5 and CCR2." (PMID 40581668, 2025). "Wildtype (WT) and Ccr2–/– mice were infected intraperitoneally (IP) with 1 × 104 CFU C. violaceum and livers were harvested 5 days post-infection (DPI)." (PMID 39541153, 2024). "A recent report showed that a C-C chemokine receptor, CCR2, mediates SFTS virus binding and infection to cells and involves SFTS pathogenesis in a murine model." (PMID 39008518, 2024). "Monocyte depletion had negligible effect on cytokine production 4 h post infection, with only MIG (CXCL9) and IL-13, significantly altered in the BALF of CCR2-depleted mice compared to WT, out of the 32 quantified secreted factors." (PMID 39418302, 2024). "In contrast, ccr2 transcripts in the brain were similar in control CCL2fl/fl mice and GFAP-Cre CCL2fl/fl mice during infection." (PMID 38206985, 2024). "In summary, we found that depletion of CCR2 positive monocytes in mice led to significant increases in bacterial load in their BALF and lungs 24 to 48 hours post infection with S. aureus." (PMID 39418302, 2024). "Collectively this data indicates that dual deletion of CCR2 and CCR7 strongly inhibits iMO recruitment to the brain during infection with either LACV or HSV-1." (PMID 38658802, 2024). "Our results show that CC chemokine receptors and their ligands, which are necessary for neutrophil mobilization and recruitment to the lungs during infection, are down regulated in human CHIP carriers (e.g., CXCL1, CXCL5) and mice (e.g., CCR2, lung CCL2)." (PMID 38573824, 2024). "During infection, CCL2 recruits CCR2+ monocytes out of the bone marrow into the circulation, and ultimately into injured or inflamed tissues." (PMID 38206985, 2024). "We also saw differences between the two groups, with CCR2 more highly expressed on CD8+ T cells in naïve participants, while CD57 and CD38 were more highly expressed in those with a history of previous infection." (PMID 37604803, 2023). "Cellular infection was confined to the CD45+ compartment in both experimental groups, where neutrophils accounted for ~95% of all infected cells in CCR2−/− mice." (PMID 37017530, 2023).
infection (continued). "The chemokine-related regulation is particularly important for inducible chemokine receptors, such as CCR2 and CCR5 helping to recruit blood neutrophils, monocytes, and activated T cells to the sites of infection." (PMID 37190028, 2023). "In our previous work, we demonstrated that infection of PB B cells with EBV upregulated two inflammatory chemokine receptors, namely CCR1 and CCR2, and the expression of these chemokine receptors persisted in established LCLs." (PMID 35408790, 2022). "Using Ccr2-GFP mice, we showed that upon intranasal VACV∆C7L infection, the CCR2+ monocytes can be differentiated into Lyve1− IMs." (PMID 35351885, 2022). "One day after intranasal infection with VACV∆C7L, we observed that CCR2-GFP+ monocytes were recruited into interstitial space between blood vessel and alveolar structure." (PMID 35351885, 2022). "The IMs in lethally infected macaques uniformly expressed CCR2 and CX3CR1, indicating they were likely recruited from the vasculature in response to infection." (PMID 35271686, 2022). "Mice lacking CCL-2 or its receptor CCR-2 are characterized by a reduced Tip-DC frequency in Lm-infected spleens resulting in uncontrolled bacterial growth, thus underlining the importance of monocyte-derived dendritic cells, originating from Ly6Chigh monocytes, for the outcome of infection." (PMID 36618344, 2022). "Within the interstitial/alveolar compartment, MHCII and CCR2 levels were elevated on AMs, CD103+ cDCs, and pDCs in all infections." (PMID 34663857, 2021). "Upon challenge infection, we noted that CCR5 and XCR1 expression on CCR2+Ly6C+ monocytes was significantly increased." (PMID 34516896, 2021). "Seven-day-old neonatal ICR mice were pretreated with the CCR2 antagonist BMS (10 mg/kg) before infection with DENV2 PL046 (1 × 106) and then received an extra dosage of BMS at 2 days post-infection (dpi) and 5 dpi." (PMID 34831405, 2021). "IL-33 drives ILC-cell-dependent recruitment of CCR2+ inflammatory monocytes, which resemble the TipDCs (TNF and iNOS-producing dendritic cells) previously shown to be important for control of infection." (PMID 33929319, 2021). "A significant increase in Ki67 and CXCR3 expression by NK cells was evident, but CCR2 and CCR5 levels remained unchanged, suggesting that NK cell infiltration and proliferation occurred after znBAZ infection." (PMID 34305935, 2021). "The expression of MHCII by CD11b+ Ly6Chi cells was between 10-20% in uninfected mice and rose to >80-90% during infection, and we observed a faster upregulation of MHCII in C57BL/6 mice compared to CCR2-/- mice on day 10 p.i.." (PMID 34290699, 2021). "Ablation of CCR2 in the cDC lineage prevents this increase and results in a deficit in IAV-specific T cell responses and diminished resistance to re-infection." (PMID 34739343, 2021). "In our model, microglia downregulated CX3CR1 over the course of infection, while Ly6Chi macrophages expressed CX3CR1, with varied CCR2 expression." (PMID 34311763, 2021). "Rather, we revealed that CCR2+Ly6C+ monocytes form clusters in the splenic RP independently from cognate Ag and CD8+ TM cells, most likely in response to other infection-driven chemotactic cues." (PMID 34516896, 2021). "Upon infection of wild-type (WT) mice with A/Puerto Rico/8/34 (H1N1) virus, the vast majority of inflammatory cells present in the lungs by PID 5 were derived from CCR2+ inflammatory monocytes." (PMID 33062077, 2020). "We found that relatively few MAIT cells expressed CCR2, CCR4, CCR6, CXCR3, CXCR4, and CCR9 in the lungs, spleen, thymus, and LP both before and after infection." (PMID 32849637, 2020). "Most of the genes for chemokines/chemokine receptors (CCR2, CCR6, CCR7, CSF2RB, CX3CR1 and CXCR4) and cytokines/cytokines receptors (IL1R2, IL8, IL18, IL20RA and IL22RA2) were down-regulated after infection by vvIBDV at 3 dpi." (PMID 33110122, 2020).
infection (continued). "Conversely, previous studies have revealed that CCR2-dependent monocytes and macrophages are important in the development of CD8 TRM following infection." (PMID 31681267, 2019). "DT treatment of CCR2-DTR mice also resulted in significant decreases in DCs and macrophages in the lungs on day 7 post-infection (p.i.)." (PMID 30897162, 2019). "It remains unclear whether IM directly facilitate dissemination of C. neoformans in this acute infection model or whether the higher lymph node and brain fungal burdens in WT mice are simply a reflection of the higher lung fungal burden in these mice compared to IM-ablated CCR2-DTR mice." (PMID 30897162, 2019). "In the liver on day 7 post-infection, the expression of iNOS, IL-1β, IL-6, IL-12 p40, TNF-α, IL-10, TGF-β, CCR2, CCL2, IFN-γ and IL-4 was significantly up-regulated, and the expression of Arg-1 was down-regulated in both of MRP14-KO mice and WT mice." (PMID 29902248, 2018). "Infection studies that used CCL2−/− and CCR2−/− C57BL/6 mice suggested that CCL2 is dispensable for protection against L. major, but that another CCR2 ligand is required." (PMID 29097502, 2018). "Interestingly, the IMD peptides released from macrophages may prevent further infiltration of macrophages into the local tissue by downregulating CCR2, which may represent a feedback loop that maintains the immune balance that was previously disrupted in response to the severe infection." (PMID 29980671, 2018). "For monocytes, this suggests that about 70% of the infiltration in response to TMEV infection is dependent upon the CCL2:CCR2 axis and about 30% requires the CCL7:CCR2 axis." (PMID 29202854, 2017). "C-C motif chemokine ligand 2 (CCL2), also known as monocyte chemoattractant protein (MCP)-1, binds to the chemokine receptors CCR2 and CCR5, and is an important regulator of monocyte/macrophage trafficking during infection or in the presence of inflammation." (PMID 28421067, 2017). "While CCR2 and CCR5 were only increased in the CD4+ TEM cell subset after infection, expression of CXCR6 and CD11c was much more abundant in CD8+ TEM cells." (PMID 27272720, 2016). "Recruited Ly6Chi monocytes co-expressing C-C chemokine receptor type 2 (CCR2) are critical to governing acute and chronic stages of infection." (PMID 26984535, 2016). "When analyzing the expression of the selected homing molecules in the activated TEM cell subset, there was a higher percentage of CCR5, CCR2 and CD11c in the CD4+ CD44+ TEM cells at 10 and/or 14 days post-infection than in the control group." (PMID 27272720, 2016). "Genes involved in the control of cell migration were also represented in the HP1 list (e.g. Ccr2, Ccr5, Itga1, Itgb1, Gpr183, Rgs16), with some having an essential role in the recruitment of CD8 T cells in the lung following infection by a pathogen." (PMID 27883012, 2016). "To understand the impact of reduced MC numbers during infection with L. pneumophila, we analysed cytokine profiles in the bronchoalveolar lavage fluid (BALF) of CCR2-/- mice." (PMID 27300652, 2016). "In general, the percentage of CCR2, CCR5, CXCR6 and CD11c (Itgax) in live CD4+ or CD4- (putative CD8+) T cells peaked 10 days after infection, when in most cases their total frequency was significantly higher than in the control group." (PMID 27272720, 2016). "A reduction of surface expression of chemokine receptors CXCR4 as well as CCR1, CCR2 and CCR5 was observed in monocytes upon their infection with endotheliotropic strains (TB40E and VHLE) and clinical isolates of HCMV." (PMID 27955674, 2016). "MCP-1 protein interacts with chemokine C-C motif receptor 2 (CCR2) to activate and recruit monocytes, macrophages, CD4+ T cells and immature dendritic cells to the site of infection." (PMID 26518714, 2015).
infection (continued). "Immunity to challenge infection was compromised in IL-4Rα- and IL-25-deficient mice, despite levels of specific antibody comparable to immune wild-type controls, while deficiencies in basophils, eosinophils or mast cells or CCR2-dependent inflammatory monocytes did not diminish immunity." (PMID 25816012, 2015). "With our infection dose, in both C57BL/6 and Ccr2-/- mice, adaptive response was evident 5 dpi because ET cells started to be detectable at higher levels at this time than those in the mice left uninfected." (PMID 26468944, 2015). "Upon infection, progress of HIV-1 has been shown to be influenced by C–C family chemokine receptors (CCR) like CCR5, CCR2 and SDF1 (a ligand of CXCR4)." (PMID 26322257, 2015). "This chemokine can also bind CCR2, the receptor for CCL2, and both it and CCL2 have additive functions in monocyte homeostasis and recruitment during infection." (PMID 26107875, 2015). "In infections of MCMV and LCMV, CCR2+ inflammatory monocyte-produced large amount of iNOS and facilitate the production of nitric oxide (NO)." (PMID 25407417, 2014). "At the early stages of infection, NOD2 signaling was shown to activate the CCL2/CCR2 axis that resulted in the recruitment of inflammatory monocytes to the site of infection, which initiated IL-12-mediated bacterial clearance." (PMID 24381573, 2013). "The upregulation in chemokine receptor expression (CCR2 and CCR5) observed during infection was abolished and CD11a expression was partially reduced when mice were treated with drugs." (PMID 23646169, 2013). "We therefore stained the formalin-fixed lung sections with antibody to CCR2, the receptor for MCP-1, present on many leukocytes, to determine if CCR2+ cells are recruited to the lungs as the yopK infection is being cleared." (PMID 23633954, 2013). "Unlike NMII infection in wild-type animals, but similar to NMII infection in CCR2 KO Gr1-depleted animals, NMI infection resulted in bacterial dissemination to the spleen at all infective doses." (PMID 23284825, 2012). "Recruitment of TLR5‐dependent immune cells via the CCL2/CCR2 pathway is critical to the development of functional CD4+ T‐cell‐mediated immunity, which helps control bacterial colonization and decreases the degree of infection." (PMID 41457476, 2026). "During infection, SFTSV targets the B cells, especially plasmablasts, of humans, which could be due to the higher expression level of SFTSV receptor, C-C motif chemokine receptor 2 (CCR2)." (PMID 40013801, 2025). "CCR2, a member of the G protein-coupled receptor (GPCR) superfamily, is widely expressed on monocytes, macrophages, activated T cells, and other cell types, and plays a critical role in coordinating the immune response to various infections." (PMID 39903705, 2025). "Specifically, this protective response is dependent on MyD88 and partially dependent on CCR2 and is not specific to the microorganism used during the initial infection." (PMID 40558085, 2025). "Upon injury or infection, the interaction between MCP-1 and CCR2 activates the signal transduction pathway, facilitating the migration and infiltration of macrophages, monocytes, microglia, and memory T lymphocytes in various diseases, including apical diseases." (PMID 40654573, 2025). "T cell recruitment to the spinal cord was influenced by CCR2 expression, as lack of CCR2 resulted in diminished numbers of T cells in the spinal cord during EV-D68 infection." (PMID 40459936, 2025). "To further explore this during Chlamydia respiratory infection, we analyzed CCR2 expression on these subsets and observed that its expression remains low and is not affected by infection." (PMID 39903705, 2025). "Early studies reported an upregulation of CCR2 expression in non-classical monocytes during severe disease to enhance migration to the infection site." (PMID 40092995, 2025). "Monocyte CCR2 expression increased following surgery, in patients with and without post-operative infections." (PMID 38655251, 2024).